SUPT20H (SPT20 homolog, SAGA complex component)
Description:
Required for MAP kinase p38 (MAPK11, MAPK12, MAPK13 and/or MAPK14) activation during gastrulation. Required for down-regulation of E-cadherin during gastrulation by regulating E-cadherin protein level downstream from NCK-interacting kinase (NIK) and independently of the regulation of transcription by FGF signaling and Snail (By similarity). Required for starvation-induced ATG9A trafficking during autophagy.
Synonyms: p38IP; C13orf19; FAM48A; FP757; SPT20; bA421P11.4; C13
Tractability: PROTAC: ubiquitination databases record sites on it; its protein half-life has been measured.
Gene: Protein-coding gene on chromosome 13 (37,009,312 to 37,059,713, reverse strand). Ensembl gene ENSG00000102710.
Subcellular location: Nucleus
Subcellular location (Human Protein Atlas): Nucleoli fibrillar center
Pathways (Reactome):
Chromatin organization: HATs acetylate histones
Gene Ontology:
Molecular function: protein binding; transcription coregulator activity
Biological process: positive regulation of DNA-templated transcription; regulation of DNA repair; regulation of RNA splicing; regulation of transcription by RNA polymerase II
Cellular component: SAGA-type complex; SAGA complex; nucleus
Genetic constraint (gnomAD): Loss-of-function variants: 54 observed, 85.9 expected, observed/expected ratio (o/e) 0.63, 90% interval 0.5 to 0.79. The upper end of that interval is the gene's LOEUF score, 0.79, which puts it in group 3 of 6, group 1 being the genes least tolerant of losing a copy. Missense variants: 686 observed, 791.78 expected, observed/expected ratio (o/e) 0.87, 90% interval 0.81 to 0.92. Synonymous variants: 258 observed, 276.92 expected, observed/expected ratio (o/e) 0.93, 90% interval 0.84 to 1.03.
Homologues: Orthologues: macaque SUPT20H (98% identical), guinea pig SUPT20H (93% identical), chimpanzee SUPT20H (91% identical), rat Supt20h (89% identical), mouse Supt20 (89% identical), dog SUPT20H (88% identical), rabbit SUPT20H (87% identical), pig SUPT20H (87% identical), tropical clawed frog supt20h (74% identical), zebrafish supt20 (67% identical), Drosophila melanogaster Spt20 (36% identical). Paralogues in human: SUPT20HL1 (57% identical), SUPT20HL2 (55% identical).
Diseases named in the same sentence as SUPT20H in open-access papers:
SUPT20H is named in the same sentence as 18 diseases in open-access papers, as found by Europe PMC text mining. Sharing a sentence is not in itself a finding about the gene and the disease. The quoted sentences say what the papers report.
glioma (2 papers, 2020 to 2021). A benign or malignant brain and spinal cord tumor that arises from glial cells (astrocytes, oligodendrocytes, ependymal cells). "Additionally, SUPT20H could serve as an independent prognostic biomarker in gliomas and multiple myeloma (MM)." (PMID 34238288, 2021). "MAPK3 and CX3CL1 were strongly positive; NFE2L2, HSP90AB1, and SUPT20H were moderately positive; and FKBP1B, BIRC5, NPC1, IKBKE, BID, and PTEN were weakly positive in glioma tissue relative to their expression levels in normal tissue." (PMID 33194668, 2020).
leukaemia (2 papers, 2016 to 2020). "Other candidates include BRINP1 (silenced in some bladder cancers), CD7 (associated with leukaemia), CSTA (encodes a stefin that functions as a cysteine protease inhibitor, suggested as a prognostic tool for cancer), and SUPT20H (a known tumour rejection antigen)." (PMID 32872585, 2020).
multiple myeloma (2 papers, 2021 to 2024). "Among the proteins not previously linked to MM were three members (TAF5L, SUPT7L and SUPT20H) of the SAGA complex, a posttranslational regulator of MYC transcriptional activity that is important for myeloma growth." (PMID 38942927, 2024).
rheumatoid arthritis (2 papers, 2019 to 2023). A chronic, systemic autoimmune disorder characterized by inflammation in the synovial membranes and articular surfaces. "Also, results showed SUPT20H gene effects on rheumatoid arthritis." (PMID 37139670, 2023).
neuroblastoma (1 paper, 2024). Neuroblastoma (NB) is the most common solid, extracranial childhood tumor. "Among the most enriched differential gene dependencies observed in MYCN-amplified neuroblastoma as compared to all other solid tumor lineages were TADA2B, TADA1, SUPT20H, and TAF5L, along with several other members of the core and KAT modules." (PMID 38820154, 2024).
SUPT20H also shares sentences with these, for which no sentence is quoted: tumor (3 papers); infection (2); anemia (1); bladder (1); bladder cancers (1); bladder tumor (1); cancer (1); head and neck squamous cell carcinoma (1); Intellectual disability (1); lymphoma (1); oral squamous cell carcinoma (1); pancreatic cancer (1); spina bifida (1).